BDNF (brain derived neurotrophic factor)
Diseases named in the same sentence as BDNF in open-access papers (continued):
Sharing a sentence is not in itself a finding about the gene and the disease.
depression (continued). "In animal models of depression and traumatic brain injury, ICA was reported to increase the expression of BDNF and improve functional behaviors of the disease models." (PMID 34257671, 2021). "Overall, our study verified that during states of excessive oxidative stress, the PIK3CA/AKT1/NFE2L2/KEAP1 and PIK3CA/AKT1/BDNF/NTRK2 signaling pathways are suppressed, which induced OB rats to exhibit phenotypic behaviors of depression." (PMID 33935736, 2021). "OST treatment improved cognitive deficit, alleviated anxiety- and depression-like behaviors induced by OVX, and reversed OVX-induced alterations in the levels of synaptic proteins and ERα, BDNF, TrKB, p-CREB, p-Akt and Rac1 in the hippocampus." (PMID 34025413, 2021). "There have been reports that oral administration of MOOs to depressed rodent animals can increase the monoamine and brain‐derived neurotrophic factor (BDNF) levels, which suggests the alleviation of depression." (PMID 34559953, 2021). "Clinical studies of postmortem brains have reported decreased BDNF and TrkB levels in the PFC of subjects who committed suicide and patients with depression." (PMID 34577589, 2021). "The data suggested that decreased expression levels of BDNF, GDNF, and NGF were concordant with the increased anxiety and depression-like behaviours in aged male mice offspring conceived by ART." (PMID 34605773, 2021). "Our data suggest that chronic fasting for 12 weeks ameliorates depression and anxiety behaviors in T2DM rats by increasing the levels of BDNF and NT3." (PMID 33671898, 2021). "Depression model rats showed overexpression of miR-124 and down-regulation of CREB1 and BDNF in the hippocampus." (PMID 34054732, 2021). "Inflammation and aberrant concentrations of BDNF have been noted in several other psychiatric disorders that are often comorbid with AN, such as PTSD and depression." (PMID 34836413, 2021). "Especially, knockout of Pdcd4 directly upregulates BDNF expression at translational level and reverses CRS-induced depression-like behaviors." (PMID 34772918, 2021). "As in the case of BDNF, the level of CREB in the hippocampus and cortex decreases with depression and returns to normal after antidepressant therapy." (PMID 33578683, 2021). "To evaluate the role of central BDNF in obesity-related depression, after 8 weeks of high-fat diet (HFD), we examined BDNF expression in hippocampus and ventromedical hypothalamus (VMH)." (PMID 34054732, 2021). "The results of the current study showed that induction of depression reduced swimming time, SPT, BDNF levels and TrkB gene expression, but increased immobility time compared to the control group." (PMID 34046326, 2021). "A lower level of brain-derived neurotrophic factor (BDNF) and abnormality in neuroplasticity or cognitive ability which are involved in the pathogenesis of depression were proven to be connected with a high level of saturated fats in red and processed meat." (PMID 34531367, 2021). "Research results revealed alterations in miRNAs expression levels, including miR-155, targeting neurotrophic factors (brain-derived neurotrophic factor, BDNF, TGF-β) and inflammatory mechanisms in patients with depressive disorders." (PMID 33919306, 2021). "Expression of NGF, BDNF, and REST genes at both protein and mRNA levels was lower in patients with depressive disorders than in the control group." (PMID 33804468, 2021). "Expression of the NGF, BDNF, and REST genes at both protein and mRNA levels is lower in patients with depressive disorders than in the control group." (PMID 33804468, 2021). "Brain-derived neurotrophic factor (BDNF) is one of the major factors determining the bipolar disorder and depression." (PMID 33014278, 2020). "The signaling pathway comprising brain-derived neurotrophic factor (BDNF) and its specific receptor tropomyosin-receptor-kinase B (TrkB) plays a key role in the pathophysiology of depression and in the antidepressant functions of antidepressants." (PMID 29882089, 2020).
depression (continued). "However, depressive-like behaviors were not reported for mice overexpressing a nonfunctional TrkB receptor in the forebrain or for mice lacking one Bdnf allele (BDNF+/− mice), although these mice were slower to escape in the learned helplessness paradigm of depression." (PMID 32492978, 2020). "Antidepressants can increase BDNF levels in the hippocampus, while viral knockout of BNDF in specific subregions of the hippocampus can induce depression-like behaviors." (PMID 32522211, 2020). "In our study, reduced BDNF levels were detected in the PFC at 8 weeks after stroke, which is consistent with the onset of the anxiety/depression like phenotypes." (PMID 32010477, 2020). "It was concluded that BCP improves depression and memory deficit by modulating PGC-1α/BDNF pathway in a CB2R-dependent manner." (PMID 32998300, 2020). "Repeated ECS ameliorated depression-like phenotypes induced by CMS and significantly increased BDNF levels." (PMID 32579566, 2020). "The aim of the present study was to investigate the possible relationship between being depressed and BDNF and PRL genotypes, on one hand, serum BDNF and PRL levels on the other, with special reference to severity of depression." (PMID 32116853, 2020). "Stress decreases BDNF concentrations in hippocampus and PFC of animal models of depression, in line with the reduced expression of this neurotrophic factor observed at cortical, hippocampal, and peripheral level of depressed patients." (PMID 32435223, 2020). "Furthermore, decreased BDNF and TrkB levels induced by acute and chronic stress could result in dysregulation of neural development and neural plasticity, which are involved in the pathogenesis of affective disorders, such as depression." (PMID 32850808, 2020). "However, no studies available showed BDNF rs1048218 and rs1048220 associated with depression." (PMID 32351365, 2020). "Meanwhile, functions of the brain-derived neurotrophic factor (BDNF) and the other neurotrophins in the pathogenesis of depression are well known." (PMID 32351365, 2020). "Using several depression-like animal models, we found that EDC exerted antidepressant effect via regulating neurotrophic factors such as NGF and BDNF." (PMID 33364963, 2020). "In contrast to the reduced level of BDNF in the PFC and hippocampus, the concentration of the factor is elevated in mesolimbic structures in depression." (PMID 32188010, 2020). "This study aimed to investigate Brain-Derived Neurotrophic Factor (BDNF) and three Cell Adhesion Molecules (CAMs) as transdiagnostic biomarkers in AUD and depression co-morbidity." (PMID 32372985, 2020). "This study aimed to elucidate the relationship of serum BDNF, malondialdehyde(MDA), and 8-Hydroxy 2-Deoxyguanosine (8-OhdG) levels in acute stroke caseswith one-month post-stroke depression." (PMID 32206197, 2020). "Stress factors alter BDNF activity and influence the BDNF-Ras-MAPK pathway, impairing neuronal cell survival and neuroplasticity, thereby resulting in depression symptoms." (PMID 33613615, 2020). "This is also the first study demonstrating the role of BDNF-TrkB signaling in the beneficial effects of 7,8-DHF in the comorbidity of neuropathic pain and depression in rodents." (PMID 29882089, 2020). "AE beneficially altered levels of depression-related iGluRs, i.e., p-AMPA receptor, p-NMDA receptor, and other essential signaling molecules including BDNF, HCY in hippocampus and GC in serum." (PMID 33374661, 2020). "In summary, the possible antidepressant effect of metformin supports the involvement of inflammation and oxidative stress in depression via diverse signaling molecules and pathways including Nrf2, pro-inflammatory cytokines and the AMPK/BDNF and NFκB pathways." (PMID 32971941, 2020).
depression (continued). "One particular receptor involved in RTK signaling, i.e., receptor tyrosine kinase B (TrkB), and its main ligand, brain-derived neurotrophic factor (BDNF), have repeatedly been shown to be affected in stress-related disorders such as depression." (PMID 31931860, 2020). "Improves anxiety and depression symptoms by inhibiting JNK-mediated apoptosis/inflammatory signaling, oxidative stress, and increases of BDNF/VEGF in hippocampus." (PMID 33041782, 2020). "To further verify the involvement of neurotrophic pathway in the alleviation of depression-like behaviors by ZTC treatment, we also measured the related protein levels in neurotrophic pathway, including BDNF, ERK1/2, CREB, and NFκB." (PMID 32982748, 2020). "Several studies report a change of the proBDNF/BDNF ratio in neurons or cerebrospinal fluid in diverse neurocognitive disorders such as Alzheimer’s disease, major depressive disorder, autism, and affective disorders." (PMID 33324399, 2020). "Brain-derived neurotrophic factor (BDNF), vascular endothelial growth factor (VEGF), fibroblast growth factors (FGF) and VGF nerve growth factor are all involved in the pathophysiology of depression and are modulated by antidepressants." (PMID 33255237, 2020). "In particular, leptin reduces symptoms of depression and has an anxiolytic effect affecting the HPA, and stimulating brain-derived neurotrophic factor (BDNF) production and function." (PMID 33066277, 2020). "CUMS significantly reduces BDNF-TrkB signaling in OVX rats, which results in depression -like behaviors and promotes the expression of pro-inflammatory cytokines and corticosterone." (PMID 33109198, 2020). "To investigate the effect of AE on depression-related signal molecules, we measured levels of HCY and BDNF in hippocampus, and GC in serum." (PMID 33374661, 2020). "Thus, NLRP1 inflammasome could affect the levels of BDNF in stress-induced depression model." (PMID 32513185, 2020). "Consequently, we hypothesized that BDNF in the mPFC modulates depression-like behaviors." (PMID 32532322, 2020). "Studies over the past years suggest that the methylations of some specific genes such as BDNF, SLC6A4, and NR3C1 play an important role in the development of depression." (PMID 33101076, 2020). "fRG also alleviated EC-induced depression-like behaviors in FST, TST, and NF-κB+/Iba1+ cell populations and EC-suppressed BDNF+/NeuN+ cell population in the hippocampus more strongly than RG." (PMID 32224881, 2020). "Additional studies are required to establish the patterns and significance of interaction between Sigma1R, BDNF, and GSK-3β in the pathogenesis of depressive disorders." (PMID 32992988, 2020). "Little is known on levels of BDNF and CAMs in patients with co-occurrence of AUD and depressive disorder." (PMID 32372985, 2020). "Stimulating the dorsolateral prefrontal cortex can significantly increase the Brain-Derived Neurotrophic Factor (BDNF) and decrease the symptoms of depression, anxiety, stress, and craving." (PMID 32477481, 2019). "Zinc has been shown to influence brain-derived neurotrophic factor (BDNF) activities, which were found to be related to depression, and to affect depression by reducing several makers of inflammation, such as C-reactive protein or interleukin-6." (PMID 30781841, 2019). "Brain-derived neurotrophic factor (BDNF) is a member of the neurotrophin protein family and is involved in the pathophysiological symptoms of depression." (PMID 31130833, 2019). "Thus, it has been speculated that BDNF may be a biomarker of depression." (PMID 31231295, 2019). "Both miRNAs regulate the transcripts of the brain-derived neurotrophic factor (BDNF), which is related to exercise effects in the human body as well as depression." (PMID 31191331, 2019).
depression (continued). "Notably, our results strongly suggested that the reduced serum CORT levels, as well as the restored SGK1, CREB, and BDNF expressions in the frontal cortex and hippocampus, may be involved in the therapeutic action of the ethanol extract of D. alatus leaf in depression." (PMID 31540539, 2019). "In both schizophrenia and depression, the mechanism of ECT involves increased levels of BDNF, as found typically in subjects with autism." (PMID 31548888, 2019). "For instance it has been reported that BDNF and 5-HTTLPR interactions were additive in predicting lifetime depression diagnosis, however, in the current sample we had limited power to add additional factors to our model." (PMID 30967802, 2019). "Lower NT concentrations, such as serum BDNF and NGF have been shown to correlate negatively with many affective disorders including bipolar disorder, major depressive disorder, mania and obsessive compulsive disorder." (PMID 30767081, 2019). "To this aim, we measured BDNF expression and LTP as molecular and cellular markers of neural plasticity, in addition to liking- and wanting-type anhedonia as endpoints of depression-like response." (PMID 30804991, 2019). "To conclude our study, we suggest that BDNF, Wnt/β-catenin and Shh signalling plays important role in the pathophysiology of CUMS induced depression and in providing the NIC mediated antidepressant effect." (PMID 31193084, 2019). "Brain-derived neurotrophic factor (BDNF), which is a protein, is involved in the regulation of long-term potentiation, long-term depression, and memory formation." (PMID 31728242, 2019). "The objective was to investigate if high cadence cycling altered non-motor cognition and depression symptoms in individuals with Parkinson’s disease (PD) and whether exercise responses were influenced by brain-derived neurotrophic factor (BDNF) Val66Met polymorphism." (PMID 31197095, 2019). "Previous studies have employed delivery of BDNF through AAV in animal models as a potential treatment for various brain pathologies, such as depression, stroke, Alzheimer's disease, and spinal cord injury." (PMID 31787925, 2019). "Besides, altered BDNF expression may be related with the etiologies of depression." (PMID 30625977, 2019). "Brain-derived neurotrophic factor (BDNF) and its receptor, tropomyosin-related kinase B (TrkB), play key roles in the pathogenesis of depression and serve many critical functions in neuronal maturation, synapse formation, and synaptic plasticity." (PMID 31572200, 2019). "Other genes have been also found to affect different neuropsychiatric disorders such as the brain‐derived neurotrophic factor (BDNF gene), which is involved in both the pathogenesis of depression and the mechanism of action of antidepressant treatments." (PMID 30656852, 2019). "For example, Xiaoyaosan effectively regulated the expression levels of brain-derived neurotrophic factor (BDNF) and its receptors (TrkB) in the hippocampus, thereby helping to reduce CIS-induced depression." (PMID 30699999, 2019). "Furthermore, it has been reported that AASs reduce hippocampal levels of neurotrophic growth factors, including BDNF, with a consequent decline in neurogenesis and hippocampal volume, a phenomenon that might be involved in the pathogenesis of depression." (PMID 30792631, 2019). "A decreased level of BDNF in the hippocampus, PFC, or serum correlates with depression in animals and humans." (PMID 32082151, 2019). "5-HTTLPR, BDNF and the interaction of 5HTTLPR x BDNF were each entered as predictors of BSI ratings of depression." (PMID 31440532, 2019). "The ERK-pathway is the most affected in depression and reflects on deficits in ERK-directed gene expression of key mediators of mood-relating function, such as BDNF and vascular endothelial growth factor (VEGF)." (PMID 31018603, 2019).
depression (continued). "Taken together, our study replicated depression-like behavior in a rat CUMS model, and decreased the expression of BDNF and its related synaptic plasticity change in the hippocampus and the PFC, accompanied by hyperactivity of the immune response." (PMID 30429764, 2018). "In conclusion, the present study provides support that compounds such as BDNF and VEGF are important markers in treatment-resistant depression and provides new information on the dynamics of growth factors in TRD." (PMID 30190686, 2018). "A previous study reported that BDNF promoter methylation status independently correlated with the prevalence, persistence, and incidence of PSD, as well as with the worsening of depression severity over a one-year period after stroke." (PMID 30322026, 2018). "Hence, according to the neurotrophic hypothesis of depression, the presumably slower production of the BDNF protein in the RLA rats may, in turn, lead to a deficit in the synaptic release and a reduced target-derived support to promote the synaptic contacts with the mossy fibers." (PMID 30477252, 2018). "Previous studies have reported different alterations in the BDNF and proBDNF in CA1, CA3, and DG regions of the hippocampus within rodents with depression-like phenotype." (PMID 30740068, 2018). "Many chronic pain and depression studies have begun to assess roles for NF-κB, CREB, and BDNF in central sensitization." (PMID 30356873, 2018). "Although many markers for depression had been identified previously, such as CRP, tumor necrosis factor-α (TNF-α), IL-6, the brain-derived neurotrophic factor (BDNF), and so on, the predictability of a single marker was poor." (PMID 30095631, 2018). "The subsequently decreased pCREB and BDNF expression in the hippocampus of EphB2 KO mice supports the hypothesis that the downstream molecules genetically interact with EphB2 to regulate neurogenesis and suppress depression-like behaviors and cognitive deficits." (PMID 30131699, 2018). "Cortical concentrations of BDNF are reduced concomitant with disturbed LTP mechanisms in several diseases, such as Alzheimer’s disease, Parkinson’s disease, depression, anorexia, and many other diseases." (PMID 30687048, 2018). "BDNF has often been suggested to contribute to the pathophysiology of major depressive disorder (MDD), and an important correlation between MDD and BDNF levels has been established." (PMID 30322026, 2018). "Recent studies reported that BDNF/TrkB signaling activation is important for ameliorating the depression-like pathology observed by the NSF test, and it can be improved by increasing BDNF expression in the hippocampus." (PMID 30602695, 2018). "Moreover, through increases in nerve growth factors like BDNF, brain connectivity and gray matter volume in certain brain regions may increase and lead to a decrease in depression, an improvement in fatigue and possibly improve cognitive function and slow down disease progression." (PMID 29872382, 2018). "Center for Epidemiologic Studies Depression Scale (CES-D) scores were determined, NIRS was performed, and serum BDNF levels were measured in all subjects." (PMID 29321655, 2018). "Current hypotheses regarding the etiology of the depressive disorder tend to integrate monoaminergic, neuroendocrine, and immunological concepts with those based on oxidative stress, neuronal plasticity, and neurogenesis disturbances (the role of brain derived neurotrophic factor, BDNF)." (PMID 30545058, 2018). "Hence, these results indicate that H. erinaceus mycelia could be an attractive agent for the treatment of depressive disorders through the modulation of monoamine neurotransmitters and proinflammatory cytokines as well as the regulation of brain-derived neurotrophic factor (BDNF) pathways." (PMID 29951133, 2018). "The decrease of brain-derived neurotrophic factor (BDNF) has been reported in alcohol use disorder and major depression." (PMID 28837087, 2017).